BTG1 (BTG anti-proliferation factor 1)
Diseases named in the same sentence as BTG1 in open-access papers (continued):
Sharing a sentence is not in itself a finding about the gene and the disease.
non-small cell lung carcinoma (5 papers, 2015 to 2022). A group of at least three distinct histological types of lung cancer, including non-small cell squamous cell carcinoma, adenocarcinoma, and large cell carcinoma. "BTG1 expression was decreased in hepatocellular, thyroid, nasopharyngeal, esophageal, breast, colorectal, and non-small cell lung cancers, and negatively associated with aggressive behaviors." (PMID 36339000, 2022). "BTG1 expression was adversely linked to poor prognosis of patients with hepatocellular, thyroid, nasopharyngeal, esophageal, breast, or non-small cell lung cancer." (PMID 36339000, 2022). "BTG1 expression was documented as a marker for favorable prognosis in thyroid, hepatocellular, esophageal squamous cell, breast and non-small cell lung cancers." (PMID 26050197, 2015). "Overexpression of BTG1 inhibited the proliferation, migration and invasion of hepatocytes, thyroid, nasopharynx, esophagus, breast and non-small cell lung cancer cells and induced apoptosis and cell cycle arrest by downregulating the expression of Cyclin D1, Bcl-2 and MMP-9." (PMID 36339000, 2022). "Furthermore, a low number of plasma exosomes with low levels of BTG-1 have been observed in the poor differentiation group, suggesting that plasma-exosome-derived BTG-1 might be a potential biomarker for a prognosis in patients with non-small-cell lung cancer." (PMID 36230852, 2022).
B-cell lymphoma (4 papers, 2016 to 2025). "BTG1 is one of the genes recurrently affected by deletion or mutation in ALL or B-cell lymphoma cases, respectively." (PMID 26657730, 2016). "In addition, BTG1 is an anti-proliferative gene that is frequently mutated in B cell lymphomas, while GAPDH participates in glycolysis which displays greater activity during inflammation." (PMID 41208955, 2025). "In addition, BTG1 is among recurrently mutated genes detected in B-cell lymphoma samples." (PMID 26657730, 2016). "Moreover, chidamide prompts BTG1-mediated autophagy, countering chemotherapy resistance in relapsed/refractory B-cell lymphoma." (PMID 41326348, 2025).
lymphoma (4 papers, 2019 to 2023). A malignant (clonal) proliferation of B- lymphocytes or T- lymphocytes which involves the lymph nodes, bone marrow and/or extranodal sites. "Taken together, BTG1 appears to act as a negative regulator of proliferation and a tumor suppressor in lymphoma." (PMID 30350856, 2019). "For instance, c‐MYC can suppress BTG1 through miR‐17–92 to maintain sustained proliferation and a neoplastic state in lymphoma cells (Li, Choi, Casey, Dill, & Felsher, 2014)." (PMID 30350856, 2019). "Genomic profiling of B‐cell leukemia and lymphoma has put BTG1 and BTG2 in the spotlight, since both genes are frequently deleted or mutated in these malignancies, pointing towards a role as tumor suppressors." (PMID 30350856, 2019). "Recent studies have shed new light on the role of BTG1 in lymphoma pathogenesis." (PMID 30350856, 2019). "Only FOXO1, BTG1, and MYD88 were in line with expectations, indicating that the abnormal transcriptional pattern for specialized lymphoma was very complicated due to the heterogeneity of lymphoma." (PMID 37700827, 2023).
endometrial carcinoma (3 papers, 2019 to 2022). A malignant tumor arising from the epithelium that lines the cavity of the uterine body. "Expression of TMEFF2 and BTG anti-proliferation factor 1 (BTG1) was lower in primary endometrial cancer compared to the healthy endometrium, while significant overexpression was noted for ring finger protein 183 (RNF183)." (PMID 35163161, 2022). "The expression level of BTG1 in stage 4 endometrial carcinoma was significantly lower than that in stage 1, stage 2, stage 3 (stage 1 vs stage 4, P = 3.029100E−04; stage 2 vs stage 4, P = 2.382500E−03; stage 3 vs stage 4, P = 4.759200E−03)." (PMID 33041670, 2020). "Cell proliferation, wound healing, transwell invasion, and cell apoptosis assays were used to detect the effects of BTG1 on the malignant biological behavior of endometrial carcinoma cells (ECCs)." (PMID 33041670, 2020). "The results showed that, compared with the normal control group, BTG1 mRNA expression was low in primary endometrial cancer tissues (P = 1.91589999420927E−09)." (PMID 33041670, 2020). "Through in vitro studies we explored the effect of BTG1 on the malignant biological behavior of endometrial cancer cells (ECCs) and epithelial-to-mesenchymal transition (EMT)." (PMID 33041670, 2020). "BTG1 could be another potential endometrial cancer biomarker." (PMID 35163161, 2022). "Since BTG1 is a tumor suppressor and the Ishikawa cell line is derived from endometrial carcinoma, lack of BTG1 expression was an expected finding." (PMID 31324015, 2019).
esophageal cancer (3 papers, 2020 to 2023). A primary or metastatic malignant neoplasm involving the esophagus. "In addition, the low expression of BTG1 has been reported to be associated with aggressive features and/or a worse prognosis of thyroid cancer, esophageal cancer, and squamous cell skin carcinoma." (PMID 36230852, 2022). "In contrast, a body of evidence indicated that BTG1 expression was negatively correlated with tumor invasion, lymph node metastasis, clinic stage, histological grade, pathological differentiation, or a low survival rate of patients with hepatocellular, thyroid, breast, or esophageal cancer." (PMID 33330092, 2020). "In the CHOL, esophageal carcinoma (ESCA), glioblastoma multiforme (GBM), HNSC, KIRC and LUSC, BTG1 expression was higher in tumor tissue than in normal tissue (all P values < 0.05)." (PMID 38062199, 2023).
glioblastoma (3 papers, 2019 to 2024). The most malignant astrocytic tumor (WHO grade IV). "Together, these results indicate that BTG1 inhibits glioblastoma cell proliferation, migration and invasion." (PMID 30787206, 2019). "In this study, we demonstrate that PUM2 positively promotes glioblastoma cell proliferation and migration mainly by repressing the expression of tumor suppressor gene BTG1." (PMID 30787206, 2019). "To clarify BTG1’s role in the malignant behaviors of glioblastoma cells, we overexpressed BTG1 in U-251MG and U-87MG cell lines." (PMID 30787206, 2019). "Here, we investigated PUM2’s role in glioblastoma development and its relationship with the cell cycle regulator BTG1." (PMID 30787206, 2019). "More importantly, we identify PUM2 as one of the key regulators of BTG1 expression since knockdown of PUM2 in glioblastoma cells gives rise to increased expression of BTG1." (PMID 30787206, 2019). "Taken together, our findings suggest that glioblastoma cells acquire their malignant properties probably due to down regulation of BTG1 by PUM2." (PMID 30787206, 2019). "Furthermore, vortioxetine treatment after gene silencing revealed that BTG1 knockdown attenuated vortioxetine’s anti-glioblastoma efficacy." (PMID 39304781, 2024). "Our results suggest that PUM2 promote glioblastoma development via repressing BTG1 expression." (PMID 30787206, 2019). "Taken together, our findings indicate that elevated PUM2 expression and subsequent down regulation of BTG1 is one of the molecular characteristics of glioblastoma, suggesting that PUM2 and its downstream cellular pathways can be a potential pharmacotherapeutic target." (PMID 30787206, 2019). "In addition, glioblastoma cells with PUM2 knockdown had one-fold higher BTG1 mRNA expression than the control cells." (PMID 30787206, 2019). "Knockdown of PUM2 led to increased BTG1 protein expression in glioblastoma cells." (PMID 30787206, 2019). "Interestingly, knockdown of BTG1 not only completely reverses the effect of PUM2 knockdown but seems to over restore the capability of proliferation in glioblastoma cell." (PMID 30787206, 2019). "In addition, knockdown of BTG1 restored the capabilities of migration and invasion in glioblastoma cells with PUM2 knockdown." (PMID 30787206, 2019). "Over-expression of BTG1 suppressed glioblastoma cell migration and invasion." (PMID 30787206, 2019). "Our results indicate that activities of PUM2 are critical molecular characteristics of glioblastoma cells and BTG1 is involved in PUM2 downstream cellular pathways, suggesting PUM2 and BTG1 can be the potential pharmacotherapeutic targets in treatment of glioblastoma." (PMID 30787206, 2019). "Here we hypothesize that PUM2 promote glioblastoma development probably by negatively regulating BTG1 expression." (PMID 30787206, 2019). "To figure out whether BTG1 also contributes to the function of glioblastoma cells, we further tested the migration and invasion capabilities in BTG1 over-expressing glioblastoma cells." (PMID 30787206, 2019). "In the glioblastoma cells, as demonstrated in our study, the net effect is suppression of cell growth which is probably due to down regulation of tumor suppressor genes such as BTG1." (PMID 30787206, 2019). "Furthermore, knockdown of BTG1 reverses the effect of PUM2 knockdown on glioblastoma cell proliferation and migration." (PMID 30787206, 2019). "Interestingly, knockdown of PUM2 leads to increase of BTG1 expression in glioblastoma cells." (PMID 30787206, 2019). "Furthermore, PUM2 negatively regulates BTG1 expression in glioblastoma cells." (PMID 30787206, 2019). "To test whether BTG1 is the critical mediator of PUM2 on glioblastoma development, we knocked down BTG1 in glioblastoma cells with PUM2 knocked down." (PMID 30787206, 2019). "Compared to control, over-expression of BTG1 significantly reduced cell proliferation by counting cell number and using CCK-8 assay, indicating over-expression of BTG1 suppressed glioblastoma proliferation." (PMID 30787206, 2019).
glioblastoma (continued). "Therefore, our results indicate that BTG1 is the critical target of PUM2 and its down regulation by PUM2 contributes to glioblastoma development." (PMID 30787206, 2019).
glioma (3 papers, 2015 to 2026). A benign or malignant brain and spinal cord tumor that arises from glial cells (astrocytes, oligodendrocytes, ependymal cells). "Similarly, BTG1 contributes to the growth arrest of glioma cells through the regulation of cyclin D1 and p21 expression." (PMID 42080092, 2026). "There is a low expression of BTG1 in gliomas, and it has a tumor suppressing effect in this case." (PMID 33041670, 2020).
metastatic cancers (3 papers, 2015 to 2022). A carcinoma which has spread from the original site of growth to another anatomic site. "Here, we found that BTG1 protein was mainly localized in the cytoplasm of superficial mucosa, infiltrating inflammatory cells, deep propria glands, fundic glands and primary and metastatic cancers, suggesting that BTG1 expression pattern had cellular specificity." (PMID 26050197, 2015). "BTG1 protein was positively detected in colorectal mucosal epithelium, infiltrating inflammatory cells, macrophages, lymphoid follicle, adenoma, well-, moderately- and poorly-differentiated, and mucinous adenocarcinoma, metastatic cancers in lymph node and liver." (PMID 27447746, 2017). "BTG1 protein was distributed in the cytoplasm of infiltrating inflammatory cells, deep propria glands, fundic glands, well-, moderately-, poorly-differentiated, and signet ring cell carcinomas, and metastatic cancer in lymph node, occasionally in the superficial mucosa." (PMID 26050197, 2015). "Furthermore, metastatic cancers in lymph node showed a higher BTG1 expression than primary cancers, which could be explained by a similar BTG1 expression between primary and metastatic cancers, and its positive correlation with lymph node metastasis." (PMID 26050197, 2015). "According to its frequency and density, BTG1 expression was statistically lower in primary cancers than adjacent NNM and metastatic cancers in lymph node (p < 0.05)." (PMID 26050197, 2015). "BTG1 expression was detectable in gastric NNM (52.9%, 305/577), primary cancers (27.7%, 170/613), and metastatic cancers in lymph node (48.6%, 86/177), respectively." (PMID 26050197, 2015). "BTG1 expression was detectable in colorectal non-neoplastic mucosa (NNM, 3.8%, 18/475), adenoma (47.7%, 52/109), primary cancers (65.6%, 318/485), and metastatic cancers in lymph node (54.4%, 80/147) and liver (59.1%, 13/22), respectively." (PMID 27447746, 2017).
thyroid cancer (3 papers, 2015 to 2022). "Various studies showed that BTG1 overexpression suppressed proliferation, migration and invasion, and induced apoptosis and cell cycle arrest of lung, kidney, breast, esophageal, hepatocellular, nasopharyngeal, and thyroid cancers with Cyclin D1, Bcl-2, and MMP-9 hypoexpression." (PMID 33330092, 2020).
triple-negative breast carcinoma (3 papers, 2022 to 2023). An invasive breast carcinoma which is negative for expression of estrogen receptor (ER), progesterone receptor (PR), and human epidermal growth factor receptor 2 (HER2). "In addition, hsa-miR-27a-3p has been identified as an onco-miR and promotes proliferation and migration of colorectal and triple negative breast cancer cells through targeting BTG-1 and GSK3β, respectively (C. Su, Huang, Liu, Liu, & Cao, 2019)." (PMID 37533517, 2022).
brain tumor (2 papers, 2007 to 2020). "Notably, we observe an increase in Btg1 knockout MBs of cells positive for CD15 that labels tumor stem cells in brain tumors as well as in MBs." (PMID 32231994, 2020). "Notably, although Btg1 is expressed in the developing and adult brain, its involvement in brain tumors has been investigated only in gliomas." (PMID 32231994, 2020).
colitis (2 papers, 2019 to 2020). Inflammation of the colon. "miR-301a promotes intestinal inflammation and colitis-associated cancer development by inhibiting BTG1." (PMID 31316397, 2019). "In addition, miR-301a can promote intestinal inflammation and colitis-correlated cancer progression via targeting BTG1." (PMID 32508527, 2020).
colorectal metastatic cancer (2 papers, 2020 to 2022). "According to the literature, colorectal metastatic cancer in lymph node showed more BTG1 expression than in primary cancer." (PMID 33330092, 2020).
diffuse large B-cell lymphoma (2 papers, 2012 to 2016). "In contrast, BTG1 mutations have frequently been found in diffuse large B-cell lymphoma, arguing that other mutation mechanisms may target BTG1 in more maturated B-lineage malignancies." (PMID 22359517, 2012). "The BTG1 gene has been reported to be affected by deletions in approximately 10% of the BCP-ALL cases, and to be targeted by nonsense and missense point mutations in diffuse large B-cell lymphoma." (PMID 22359517, 2012).
head and neck cancer (2 papers, 2020 to 2021). A primary or metastatic malignant neoplasm affecting the head and neck. "This aligns with our results, which show that head and neck cancer patients with higher levels of BTG1 had significantly better survival after taking paclitaxel." (PMID 33654134, 2021).
kidney cancer (2 papers, 2017 to 2020). Primary or metastatic malignant neoplasm involving the kidney. "As for clear cell renal cell carcinoma, which account for the majority of kidney cancer, BTG2 and BTG4 were reduced, while BTG1 was elevated in clear cell renal cell carcinoma compared with normal kidney tissue group." (PMID 28922388, 2017).
lung adenocarcinoma (2 papers, 2017 to 2022). A carcinoma that arises from the lung and is characterized by the presence of malignant glandular epithelial cells. "According to Selamat and Okayama’s analyses, BTG1 was lower in lung adenocarcinoma, but higher in squamous cell lung carcinoma in Talbot’s study." (PMID 28922388, 2017).
mucinous adenocarcinoma (2 papers, 2017 to 2020). An invasive adenocarcinoma composed of malignant glandular cells which contain intracytoplasmic mucin. "According to the TCGA database, BTG1 mRNA expression was lower in well-, moderately, and poorly differentiated than mucinous adenocarcinomas and positively correlated with ras or BRAF mutation (P < 0.05)." (PMID 33330092, 2020). "In TCGA data, BTG1 mRNA expression was lower in well-, moderately, and poorly differentiated than in mucinous adenocarcinomas (P < 0.05)." (PMID 33330092, 2020).
neuroblastoma (2 papers, 2025). Neuroblastoma (NB) is the most common solid, extracranial childhood tumor. "Knockdown of BTG1 in GD2-CAR-IL-15 NKT cells enhanced tumor elimination in a neuroblastoma mouse mode." (PMID 40315330, 2025). "Recently, a phase 1 trial study of GD2-CAR-IL-15 NKT in refractory neuroblastoma showed that BTG1 is a key driver of hyporesponsiveness in exhausted NKT and T cells." (PMID 40315330, 2025).
pancreatic cancer (2 papers, 2022 to 2023). "Interestingly, genes associated with pancreatic cancer such as MALAT1 (noncoding RNA), CTRB2 (serine protease), CST7 (cysteine peptidase inhibitor), and BTG1 (anti-proliferation factor) were picked in multiple topics." (PMID 36968070, 2023).
pancreatic ductal adenocarcinoma (2 papers, 2020 to 2022). An infiltrating adenocarcinoma that arises from the epithelial cells of the pancreas. "For example, the low expression of BTG1 might be involved in the progression of pancreatic ductal adenocarcinoma, suggesting that BTG1 might be a poor prognostic marker of the survival rate in cancer." (PMID 36230852, 2022). "The low expression of BTG1 may be involved in the occurrence and development of pancreatic ductal adenocarcinoma." (PMID 33041670, 2020).
renal carcinoma (2 papers, 2014 to 2017). A carcinoma arising from the epithelium of the renal parenchyma or the renal pelvis. "In renal carcinoma cells, an increase in miR-454-3p displayed a marked decrease in BTG1 via a direct interaction with the 3′-UTR of BTG1 mRNA." (PMID 28621736, 2017). "Because BTG1 is involved in the regulation of cell cycle progression and responds to IR, we examined the effects of BTG1 expression on the radiosensitivity of renal carcinoma 786-O cells." (PMID 25115181, 2014). "To investigate whether BTG1 functions as a responder to IR, we examined the protein levels of BTG1 in response to 5 Gy of X-rays in renal carcinoma 786-O cells by Western blot analysis." (PMID 25115181, 2014). "With these precedents, we tested whether the BTG1 could be regulated by miRNAs upon irradiation and how the cellular radiosensitivity in renal carcinoma cells could be affected by the changes of miRNAs targeting BTG1." (PMID 25115181, 2014).
renal cell carcinoma (2 papers, 2014 to 2015). "However, the functions of BTG1 in renal cell carcinoma (RCC) remain unclear." (PMID 26622543, 2015). "Some studies have shown that BTG1 is involved in the general processes of cell cycle control and in cellular responses to stress, though a specific role for BTG1 in renal cell carcinoma has not been determined." (PMID 25115181, 2014).
adenoma (1 paper, 2017). A neoplasm arising from the epithelium. "In the present study, BTG1 protein was mainly localized in the cytoplasm of colorectal mucosal epithelium, infiltrating inflammatory cells, macrophages, lymphoid follicle, adenoma, cancer and hepatocytes." (PMID 27447746, 2017).
allergic reactions (1 paper, 2020). "We present evidence that NF-κB-miR-183-5p-BTG1 axis can serve as target for development of anti-allergy drug." (PMID 32733254, 2020). "We provide evidence NF-κB-miR-183-5p-BTG1 axis can be a target for the development of anti-allergy drugs." (PMID 32733254, 2020). "BTG1 prevented antigen from inducing molecular features of in vitro allergic reactions." (PMID 32733254, 2020).
Burkitt lymphoma (1 paper, 2019). A rare form of malignant mature B-cell non-Hodgkin lymphoma. "In Burkitt lymphoma (BL) subtype with RBL2/p130 mutation, the BTG1 expression is suppressed, resulting in loss of growth control." (PMID 30350856, 2019).
chronic kidney disease (1 paper, 2023). Impairment of the renal function secondary to chronic kidney damage persisting for three or more months. "Targeting BTG1 holds promise for future interventions aimed at addressing angiogenesis deficiency in RIF, with the ultimate goal of improving outcomes for individuals with chronic kidney disease." (PMID 37949939, 2023).